STAB1 (stabilin 1)
Diseases named in the same sentence as STAB1 in open-access papers (continued):
Sharing a sentence is not in itself a finding about the gene and the disease.
dementia (1 paper, 2025). Loss of intellectual abilities interfering with an individual's social and occupational functions. "Other genes previously associated with AD or dementia were differentially expressed in both brain regions: CHI3L2, FCGBP, GLI1, STAB1, APOC1, MYO7A, and long non‐coding RNA JHDM1D‐AS1." (PMID 39876821, 2025).
esophageal cancer (1 paper, 2017). A primary or metastatic malignant neoplasm involving the esophagus. "Here we showed that the migration of TE-1cells was inhibited by knockdown of STAB1 in in vitro Transwell assay, suggesting STAB1 is one of the contributors for esophageal cancer invasion." (PMID 28147311, 2017). "Accumulated evidences suggested that STAB1 is an oncoprotein in various tumors; however, the exact function is still unknown in esophageal cancer." (PMID 28147311, 2017). "The overlapping analysis for DEGs of TE-1 and MDA-MB-231cells showed that there is no common gene identified in all three comparisons while only quite few common genes were found in two comparisons, suggesting STAB1 plays different regulatory roles in esophageal cancer development." (PMID 28147311, 2017).
familial hypercholesterolemia (1 paper, 2020). An inheritable form of hyperlipidemia, in which there are excess lipids in the blood. "Finally, a stabilin-1-mediated pro-atherogenic effect has been suggested, as stabilin-1-expressing circulating monocytes of patients with familial hypercholesterolemia (FH) have shown increased CD36-mediated uptake of oxLDL." (PMID 32226456, 2020).
Granuloma (1 paper, 2020). A compact, organized collection of mature mononuclear phagocytes, which may be but is not necessarily accompanied by accessory features such as necrosis. "STAB1 codes for a transmembrane receptor that is expressed in endothelial cells and lymph nodes, with functions in angiogenesis, lymphocyte homing and cell adhesion which are key aspects in the chronicity of the granuloma." (PMID 33276795, 2020).
head and neck cancer (1 paper, 2021). A primary or metastatic malignant neoplasm affecting the head and neck. "In a series of 54 head and neck cancer patients, elevated expression of stabilin-1 (CLEVER-1) was associated with shorter recurrence-free survival." (PMID 34885098, 2021).
invasive breast carcinoma (1 paper, 2025). A carcinoma that infiltrates the breast parenchyma. "Additionally, a clinicopathological investigation of invasive breast cancer showed a high expression of STAB1+ macrophages that correlated with poor survival." (PMID 41007347, 2025). "For instance, in a cohort of invasive breast cancer, an increased population of CD68+ and STAB1+ macrophages was observed within the intra-tumoral compartment, a region characterized by extensive stromal–parenchymal interactions." (PMID 41007347, 2025).
meningioma (1 paper, 2023). A generally slow growing tumor attached to the dura mater. "STAB1 was the only shared antigen yielding both meningioma-associated HLA class I and II ligands." (PMID 37368072, 2023).
myocardial infarction (1 paper, 2025). Gross necrosis of the myocardium, as a result of interruption of the blood supply to the area, as in coronary thrombosis. "Additionally, Stab1, a receptor that directly recognizes PS, has been reported to be upregulated in macrophages during myocardial infarction." (PMID 41590849, 2025). "However, it is unclear whether Stab1 contributes to cytokinesis during myocardial infarction." (PMID 41590849, 2025).
Nephropathy (1 paper, 2018). A nonspecific term referring to disease or damage of the kidneys. "Under physiological conditions, only a simultaneous deletion of Stab1 together with its close homolog Stab2 results in glomelurofibrotic nephropathy possibly by impairing the clearance of profibrotic cytokine GDF-15 in the liver." (PMID 30349531, 2018).
neuroblastoma (1 paper, 2022). Neuroblastoma (NB) is the most common solid, extracranial childhood tumor. "Notably, STAB1 has been identified as a potential therapeutic target in neuroblastoma to block the tumorigenic effects of osteonectin." (PMID 36176417, 2022).
non-alcoholic steatohepatitis (1 paper, 2023). "The involvement of both Stab1 and Stab2 in the development and progression of non-alcoholic steatohepatitis (NASH) models has not been comprehensively studied." (PMID 37446152, 2023).
oral cancers (1 paper, 2025). "Further investigations into the role of STAB1 in immunosuppressive macrophages demonstrated that the enrichment of STAB1+ TAMs are associated with poor prognosis in breast, bladder, and oral cancers." (PMID 41007347, 2025).
papillary thyroid carcinoma (1 paper, 2025). "In papillary thyroid carcinoma, enhanced M2 macrophage recruitment identified by LYVE-1 (a lymphatic vessel-specific glycoprotein), CD206, and STAB1 was observed as the disease progressed." (PMID 41007347, 2025). "Additionally, deletion of the STAB1 gene in papillary thyroid carcinoma (PTC) by CRISPR/Cas9 decreased the CD4+/CD8+ T-cell ratio, further supporting the role of STAB1+ macrophages in immune regulation." (PMID 41007347, 2025).
preinfarction angina (1 paper, 2022). "In addition, the percentage of stabilin-1+ cells in the WP of the spleen correlated with the presence of LV aneurysm and preinfarction angina (r = −0.6; p = 0.03)." (PMID 35629341, 2022).
psoriasis (1 paper, 2024). An autoimmune condition characterized by red, well-delineated plaques with silvery scales that are usually on the extensor surfaces and scalp. "Psoriasis‐like changes are reduced in Stab2‐deficient mice with increased TGFBi levels compared to Stab1‐deficient mice, while scleroderma‐like effects show no differential impact." (PMID 38946049, 2024).
sarcoidosis (1 paper, 2020). Sarcoidosis is a multisystemic disorder of unknown cause characterized by the formation of immune granulomas in involved organs. "This study corroborates previous genomic markers suggested for sarcoidosis such as STAB1, HBEGF, FABP4 and NOTCH4, with HBEGF and NOTCH4 only expressed in lung granulomas." (PMID 33276795, 2020). "Our previously conducted epigenetic studies in sarcoidosis identified IL6ST and STAB1 as part of a miRNA-derived gene signature for complicated sarcoidosis." (PMID 33276795, 2020). "In the current study, IL6ST was significantly dysregulated only in TB granulomas (FC − 1.42 and p 0.0008), while STAB1 gene was significantly downregulated in lymph nodes in sarcoidosis (FC − 1.64, p 0.0014)." (PMID 33276795, 2020).
thyroid cancer (1 paper, 2022). "The mouse thyroid cancer model used in this study recapitulates the inflammatory nature of aggressive BRAFV600E thyroid cancer with the massive recruitment of immunosuppressive macrophages expressing typical M2-like markers, such as CD206, F4/80, CD11b and Stab1." (PMID 35453506, 2022).
wasting syndrome (1 paper, 2021). "TCDD can induce fatal wasting syndrome in rats, characterized by loss of adipose and body weight, and increased serum lipid levels, and STAB1 overexpression could be associated with this degradation of stored fat that occurs with acute exposure to high levels of TCDD." (PMID 33849548, 2021).
tumor (73 papers, 2010 to 2026). "Remarkably, the contribution of STAB1 in cell adhesion and extravasation mechanisms also increases the susceptibility of tumor emboli and thrombosis development, underscoring a broad and detrimental role of STAB1 throughout disease progression." (PMID 41007347, 2025). "Herein, we discuss the role of STAB1 in tumor-associated macrophages in relationship to disease progression and patient outcome." (PMID 41007347, 2025). "Among the M2 macrophage surface receptors, STAB1 is abundantly expressed on TAMs and implicated in protumor pathways during tumor growth and metastasis." (PMID 41007347, 2025). "The questions regarding the regulatory role of STAB1 in modulating immune cell trafficking, tumor-associated angiogenesis, and macrophage polarization in various cancer types remain to be defined." (PMID 41007347, 2025). "This review provides a comprehensive overview of tumor-associated macrophages and the role of Stabilin-1-expressing macrophages in tumor development and metastasis." (PMID 41007347, 2025). "Studies indicate that STAB1 is associated with tumor progression by contributing to pathways involved in altered T-cell infiltration, defective antigen presentation, and resistance to immune checkpoint inhibitors." (PMID 41007347, 2025). "Although the role of STAB1 in cancer development and metastasis remains to be defined, STAB1 signaling in tumor-associated macrophages and downstream immune modulation are thought to be crucial mechanisms." (PMID 41007347, 2025). "Noticeably, mounting evidence from several clinical cohorts and preclinical studies highlights the role of STAB1+ TAMs in mechanisms underlying tumor progression, thereby supporting STAB1 as a potential therapeutic target." (PMID 41007347, 2025). "To date, various clinical cohorts and preclinical rodent studies have shown that STAB1 inhibition is associated with elevated anti-tumor T-cell responses." (PMID 41007347, 2025). "Deficiency and targeting of Stabilin-1, which is expressed by liver sinusoidal endothelial cells and subsets of macrophages, has been shown to improve anti-tumor immune responses in preclinical and early clinical studies." (PMID 38275881, 2024). "STAB1 is an identified oncogene whose increased expression promotes tumorigenesis and tumor progression 30, and it is associated with poor prognosis in many cancers." (PMID 33758613, 2021). "This strategy successfully identified 20 putative tumor-associated candidate genes in TAFs; some were previously reported as tumor-associated in TAFs, such as Stat3, Stab1, and Nfkbib." (PMID 29228606, 2017). "Similarly, the high abundance of STAB1+ TAMs in the early stage of gastric adenocarcinoma (T1 or Tumor node metastasis (TNM) stage 1) is associated with poor survival." (PMID 41007347, 2025). "STAB1 + Mɸ displayed a transcriptional resemblance to CAMLs, which concurrently expressed genes associated with both Mɸ and epithelial cells, and exhibited copy number alterations (CNAs) similar to those found in tumour cells." (PMID 38782901, 2024). "Moreover, intratumoral stabilin-1+ Mφ density was positively associated with tumor stage (P < 0.01) and histological grade (P < 0.01), and emerged as an independent prognostic factor for OS (HR 2.371; P < 0.0001), but not for RFS (HR 1.491; P = 0.061)." (PMID 31302753, 2020). "Additionally, loss of Stabilin-1 and -2 as well as CD32b was also observed around the tissues surrounding the tumor in HCC patients." (PMID 32848838, 2020). "Stabilin-1 is a multi-functional scavenger marker for specialized tumor-associated Mφs." (PMID 31302753, 2020). "These tumor-associated macrophages (TAMs) share many common features with the alternatively activated macrophages, showing a typical M2 marker profile with high expression of C-type lectin receptors, stabilin-1, and Arg-1." (PMID 23316105, 2012).
tumor (continued). "Similarly, in triple‐negative breast cancer, this axis drives the recruitment of monocytes to tumor sites, where they differentiate into a specific subpopulation of lipid‐associated macrophages characterized by STAB1 and TREM2 expression, which exhibit immunosuppressive properties." (PMID 40692664, 2025). "Thus, the characterization of molecular mechanisms underlying immunosuppressive STAB1+ TAMs in tumor growth and metastasis may drive the development of novel anti-cancer approaches." (PMID 41007347, 2025). "Our data showed that the density of stromal stabilin-1+ Mφs is much higher than that of intratumoral stabilin-1+ Mφs, but that only intratumoral stabilin-1+ Mφ density is a predictor of poor prognosis and is positively associated with tumor stage and histological grade." (PMID 31302753, 2020). "Moreover, tumor-associated ECs can preferentially promote the recruitment of Tregs by the upregulation of the multifunctional endothelial receptor CLEVER-1/stabilin-1, thus suggesting that tumor endothelium can support both the recruitment and the survival of immunosuppressive T cells." (PMID 29371595, 2018). "STAB1 interacts with different ligands and modulates a wide range of functions including cell trafficking, endocytosis, homeostasis, angiogenesis, and tumor vascularization." (PMID 41007347, 2025). "The tissue repair-promoting stabilin-1+Ly6Chi mouse monocyte subset has been shown to expand following the resection of the primary tumor and to promote lung metastasis originating from circulating tumor cells." (PMID 40427136, 2025). "The immunosuppressive role of STAB1 is evident in TAMs, where it promotes tumor progression by inhibiting cytotoxic T-cell activity and enhancing regulatory T-cell recruitment." (PMID 41007347, 2025). "The deficiency of STAB1 induced the elevation of inflammatory cytokines (IL1β, IL2, IL12p70, TNFα) and chemokines (CCL3, CCL4, CCL5) in tumor-bearing mice." (PMID 41007347, 2025). "In other studies, using conditional Stab1 KO mice with bone marrow chimeras and cell depletion experiments in multiple solid tumors demonstrated significant impairment in tumor development with altered STAB1 expression in macrophages." (PMID 41007347, 2025). "Experimental models using Stab1 KO mice resulted in a reduction in tumor growth and metastasis with enhanced antitumor immunity, underscoring its role as an immunosuppressive TAM." (PMID 41007347, 2025). "Macrophages_LYVE1 also expressed high levels of LYVE1, RNASE1, STAB1, CD163, and MARCO, which are associated with macrophage function and tumour immunosuppression." (PMID 40759637, 2025). "This study suggests that the targeting of Stab1 should be considered in a tumor- and organ-specific manner." (PMID 38275881, 2024). "This suggests that anti-Stab1 therapies should be considered with respect to the tumor entity or target organs." (PMID 38275881, 2024). "We suggest that the organ- and tumor-specific effects of anti-Stab1 therapies should be further considered and analyzed in future human studies." (PMID 38275881, 2024). "STAB1 + Mɸ were identified in the tumour resections, so we used DEA to identify a set of genes that were specific for STAB1 + Mɸ compared to tumour AIMɸ or AMɸ." (PMID 38782901, 2024). "In contrast, macrophage populations in tumour, and in particular STAB1 + Mɸ, were correlated with foetal macrophages." (PMID 38782901, 2024). "Since these studies indicated an immunosuppressive effect of Stab1 on the tumor microenvironment, targeting of Stab1 was further investigated." (PMID 38275881, 2024). "The prevalence of anti-inflammatory Mɸ, including STAB1 + Mɸ, exhibited an inverse relationship with the abundance of natural killer (NK) cells and T cells in the tumour environment; and the NK cells within the tumour exhibited reduced cytotoxic activity." (PMID 38782901, 2024).
tumor (continued). "We found that alternatively activated macrophages utilize stabilin-1 for the efficient clearance of soluble component of tumor extracellular matrix SPARC." (PMID 36960065, 2023). "STAB1 mediates endocytose ligands and is critical for cell adhesion in chronic inflammation and tumor metastasis." (PMID 37638007, 2023). "CRISPR/Cas9 inactivation of the Stabilin-1 gene in the in situ PTC model revealed an increase in the number of CD8+ T cells in the thyroid TME during tumor progression." (PMID 36230610, 2022). "In line with our data, BM-derived myeloid cells activated by IL-4/IL-13 upregulated lymphatic-specific markers Lyve-1 and stabilin-1 in several tumor models." (PMID 35442077, 2022). "Of the other studied markers and sites, patients with pulmonary metastases had low STAB1+-immunosuppressive macrophage density in their primary tumours." (PMID 34817749, 2022). "It was demonstrated that blocking STABILIN-1 on macrophages or inactivating Stab1 allowed the reactivation of CD8+ T cells within the tumor." (PMID 36230610, 2022). "Large body of evidence demonstrated that stabilin-1/CLEVER-1 can mediate cell-matrix and cell-cell interactions during primary tumor growth and in metastatic state." (PMID 36686729, 2022). "Stabilin-1 expression in TAMs was associated with poor OS, RFS, tumor stage and histological grade in patients with urothelial carcinoma." (PMID 36686729, 2022). "Clever-1/stabilin-1+ is a scavenger receptor and an adhesion molecule regulating macrophage and T regulator lymphocyte transendothelial migration as well as tumor infiltration." (PMID 33783686, 2021). "It was proposed that M2 macrophages can coordinate extracellular matrix remodeling, angiogenesis, and tumor progression by regulating SPARC extracellular concentration via stabilin-1-mediated endocytosis of SPARC." (PMID 34209679, 2021). "Multiple studies have reported that aberrant expression of STAB1 is related to the tumor progression in various types of cancer, serving as a potential molecular target for cancer therapy." (PMID 32780768, 2020). "STAB1 was involved in tumor immunity, epithelial‐to‐mesenchymal transition, metastasis and multidrug resistance." (PMID 32027093, 2020). "Its role in cancer growth and spread first became evident in Stab1–/– knockout mice, which have smaller primary tumours and metastases." (PMID 32595212, 2020). "Anti-stabilin-1 antibody treatment leads to diminished numbers of immunosuppressive leukocytes in tumors 95, indicating that stabilin-1 on macrophages participates in tumor-related immune responses." (PMID 32802188, 2020). "Targeting of stabilin-1 may therefore allow modulation of the hepatic Treg pool or prevention of tumour metastasis; indeed, genetic deficiency or antibody blockade of stabilin-1 reduces immunosuppressive leukocytes within tumours and halts tumour progression in mice." (PMID 32982772, 2020). "The macrophage mannose receptor I (MR) and Stabilin-1 (STAB1 or CLEVER-1) have been suggested to mediate cancer cell adhesion to lymphatic endothelium and their expression on tumor lymphatic vessels has been associated with increased lymph node metastases." (PMID 31963450, 2020). "Evidence has shown that the tumor microenvironment promotes upregulation of the expression of stabilin-1 in Mφs." (PMID 31302753, 2020). "Stabilin-1 was found to play a tumor promoting role in the TS/A model likely through enhanced clearance of SPARC." (PMID 31783695, 2019). "Our results suggest stabilin-1 mediated silent clearance of extracellular tumor growth-inhibiting factors (e.g. SPARC) as a mechanism of stabilin-1 induced tumor growth." (PMID 27105498, 2016). "Since some of these ligands (such as SPARC) are involved in the control of tumor progression, the regulation of their extracellular concentration by stabilin-1 can result in microenvironmental changes affecting tumor growth." (PMID 27105498, 2016).